DCK (deoxycytidine kinase)
Diseases named in the same sentence as DCK in open-access papers (continued):
Sharing a sentence is not in itself a finding about the gene and the disease.
hepatocellular carcinoma (3 papers, 2020 to 2024). A malignant tumor that arises from hepatocytes. "The activity of hepatocellular carcinoma cells was dramatically inhibited following DCK knockdown in MHCC-97H and HepG2 cell lines." (PMID 38517376, 2024). "The results of wound healing and transwell assays demonstrated a significant reduction in the migration and invasion capacity of hepatocellular carcinoma cells following DCK knockdown through transwell assay and wound healing assay." (PMID 38517376, 2024). "SNRPC, PKB, and DCK have been discovered to significantly correlate with patient outcomes and immune cell infiltration in hepatocellular carcinoma." (PMID 35659304, 2022). "Moreover, the results of cell experiments demonstrated that the downregulation of DCK markedly inhibited the malignant phenotype of hepatocellular carcinoma." (PMID 38517376, 2024). "However, the relationships between the expression of DCK, patient prognosis, and tumor-infiltrating immune cells (TIICs) in hepatocellular carcinoma (HCC) are still unclear." (PMID 32690026, 2020).
lymph node metastasis (3 papers, 2013 to 2019). "In the multivariable model, DCK expression, vascular invasion, and lymph node metastasis were significantly associated with RFS." (PMID 29113399, 2017). "Multivariable analysis showed that DCK expression, vascular invasion, and lymph node metastasis were significantly associated with RFS." (PMID 29113399, 2017). "Presence of dCK+ cells was associated with the occurrence of lymph node metastases (P < 0.005)." (PMID 31307406, 2019). "However, there was only a minor association between dCK expression and depth of tumor, lymph node metastasis or pathological stage (P=0.19, P=0.14 and 0.10 respectively)." (PMID 24649234, 2013).
meningioma (3 papers, 2017 to 2025). A generally slow growing tumor attached to the dura mater. "Apparently, the molecular mechanism underlying the sensitivity of high-grade meningioma to gemcitabine, including the role of HuR and dCK expression, is an important topic of future studies." (PMID 29207619, 2017).
non-small cell lung carcinoma (3 papers, 2006 to 2019). A group of at least three distinct histological types of lung cancer, including non-small cell squamous cell carcinoma, adenocarcinoma, and large cell carcinoma. "Similar results were reported in non-small cell lung cancer cells, suggesting that modulation of dCK and hENT1 gene expression as well as inhibition of Akt phosphorylation by pemetrexed may be involved in the improvement of gemcitabine therapeutic potential against several cell lines." (PMID 16868547, 2006).
abscess (2 papers, 2024 to 2025). An inflammatory process characterized by the accumulation of pus within a newly formed tissue cavity which is the result of a bacterial, fungal, or parasitic infection or the presence of a foreign body. "By applying this concept along with a drug-repurposing approach, we here report that administration of (R)-DI-87, a soluble, orally active, and high-affinity inhibitor of host dCK, reduces S. aureus abscess formation in a mouse model of bloodstream infection." (PMID 38512723, 2024). "Collectively, these data indicate that inhibition of mammalian dCK by (R)-DI-87 attenuates S. aureus abscess formation and disease pathogenesis in vivo." (PMID 38512723, 2024). "DI-87, a host-directed therapy drug, by inhibiting the host cell's deoxycytidine kinase, effectively reduced the apoptosis of phagocytes, enhanced the infiltration of macrophages into the abscesses, and thus decreased the formation of abscesses and bacterial load." (PMID 41162169, 2025). "Thus, we hypothesized that pharmacological inhibition of host dCK might augment phagocyte infiltration into S. aureus-derived abscesses, thereby explaining reduced bacterial burdens in (R)-DI-87-treated laboratory animals." (PMID 38512723, 2024).
acute monocytic leukemia (2 papers, 2013 to 2019). Acute monoblastic leukemia (AML-M5), is one of the most common subtypes of acute myeloid leukemia (AML) that is either comprised of more than 80% of monoblasts (AML-M5a) or 30-80% monoblasts with (pro)monocytic differentiation (AML-M5b). "The highest dCK activity was observed in human acute monocytic leukemia (THP-1) cells after incubation with the CLA-FMOR and CLA-FPIR derivatives." (PMID 31575977, 2019). "Previously, deoxycytidine kinase (dCK), a salvage pathway enzyme of nucleotide biosynthesis, was reported as an alternative molecular target for MTX by affinity purification using styrene glycinemethacrylate (SG) beads from cytoplasmic extracts of the human acute monocytic leukemia cell line THP-1." (PMID 23658798, 2013).
bladder cancer (2 papers, 2006 to 2021). "Moreover, dCK activity was related to dCK mRNA levels in bladder cancer specimens as well as in tumour xenografts, and preliminary data in esophageal tumours demonstrated a significant correlation between dCK expression and response to gemcitabine-based treatment." (PMID 16868547, 2006). "Moreover, this study was aimed at providing a preliminary characterisation of the expression pattern of hENT1, hCNT1, dCK, 5’-NT, CDA, RRM1 and RRM2 in surgical specimens of bladder cancer, in order to find a possible association between gene expression and response to gemcitabine treatment." (PMID 16868547, 2006). "Indeed, hENT1 and dCK gene expression was not significantly modulated in bladder cancer cells at low fraction affected (0.10 effect level), potentially explaining drug antagonism." (PMID 16868547, 2006).
colorectal cancer (2 papers, 2020 to 2021). A primary or metastatic malignant neoplasm that affects the colon or rectum. "For example, HCT116 colorectal cancer cells, resistant to prolonged DAC treatment, showed increased mRNA expression of secreted frizzed related protein 1 and protein expression of cytidine deaminase, while that of deoxycytidine kinase was decreased." (PMID 32194414, 2020).
Lewis Lung Carcinoma (2 papers, 2019 to 2024). "In addition, by utilizing a Lewis lung carcinoma (LLC) murine model, we evaluated the anti-tumor effect of GEM altered by a combination administration of DBD and determined the mRNA and protein expression level of dCK and P-gp in tumor tissue of LLC model mice." (PMID 31130654, 2019).
multiple sclerosis (2 papers, 2022 to 2025). A progressive autoimmune disorder affecting the central nervous system resulting in demyelination. "dCK inhibitors have demonstrated the potential to mitigate the manifestations of multiple sclerosis in mouse models, and dCK-specific PET probe accumulation has been proposed as a potential non-invasive biomarker for these inhibitors in patients." (PMID 40519286, 2025).
myeloid leukemia (2 papers, 2022 to 2024). A clonal proliferation of myeloid cells and their precursors in the bone marrow, peripheral blood, and spleen. "Similarly, the human myeloid leukemia cell line KF-19VCR lacks expression of the MDR1 gene and P-glycoprotein, and does not exhibit alterations in deoxycytidine kinase and deaminase activities, yet it remains resistant to cytarabine." (PMID 39339789, 2024).
astrocytoma (1 paper, 2013). "We have previously demonstrated GJIC-dependent bystander effects with suicide gene therapy based on the delivery of a catalytically-enhanced variant of the deoxycytidine kinase (dCK) suicide gene in a U87 model of glioblastoma-astrocytoma." (PMID 24194950, 2013).
autoimmune disease (1 paper, 2025). A disorder resulting from loss of function or tissue destruction of an organ or multiple organs, arising from humoral or cellular immune responses of the individual to their own tissue constituents. "Preclinical observations of altered immune phenotypes in dCK knockout mice prompted the testing of a dCK inhibitor for treating autoimmune diseases." (PMID 40519286, 2025).
Bladder tumour (1 paper, 2006). "Bladder tumour specimens showed an heterogeneous gene expression pattern and patients with higher levels of dCK and hENT1 had better response." (PMID 16868547, 2006).
chronic lung disease (1 paper, 2025). According to the definitions of the American and British Thoracic Societies, including pulmonary functional tests, X-rays, and CT scans for items such as fibrosis, bronchiectasis, bullae, emphysema, nodular or lymphomatous abnormalities. "Some studies indicate that in idiopathic pulmonary fibrosis (IPF), DCK is a downstream target of hypoxia and contributes to alveolar epithelial cell proliferation, while in chronic obstructive pulmonary disease (COPD), elevated DCK levels can trigger apoptosis in chronic lung disease cells." (PMID 41200180, 2025).
chronic myelogenous leukemia (1 paper, 2019). "Consistent with our present findings, HU and AZT, which are both independent of dCK activity status were previously found to elicit a synergistic cytotoxic activity against human acute lymphoblastic and chronic myelogenous leukemia cell line models." (PMID 31101804, 2019).
cutaneous melanoma (1 paper, 2020). A primary melanoma arising from atypical melanocytes in the skin. "In addition, hyperactive EZH2 mutations are reported to control cell growth and metastasis through silencing of distinct tumor suppressors, such as DCK, AMD1, and WDR19, in cutaneous melanoma." (PMID 32906688, 2020).
esophageal squamous cell carcinoma (1 paper, 2013). Esophageal squamous cell carcinoma (ESCC) is a type of esophageal carcinoma (EC) that can affect any part of the esophagus, but is usually located in the upper or middle third. "Furthermore, no studies regarding dCK expression of esophageal squamous cell carcinoma (ESCC) patients have been reported thus far." (PMID 24649234, 2013).
gallbladder cancer (1 paper, 2025). "Mutations or reduced expression of dCK have been identified in resistant gallbladder cancer cell lines, where restoring dCK levels can re-sensitize cells to the drug." (PMID 39757310, 2025).
giardiasis (1 paper, 2024). An infection of the small intestine caused by the flagellated protozoan giardia lamblia. "Ara-A, which is an even worse substrate of dCK and dGK and is mainly phosphorylated by adenosine kinase in mammalian cells, could perhaps be the most interesting option of the two drugs against giardiasis." (PMID 39607702, 2024).
glioma (1 paper, 2021). A benign or malignant brain and spinal cord tumor that arises from glial cells (astrocytes, oligodendrocytes, ependymal cells). "Another PET imaging strategy using radiolabeled substrates for deoxycytidine kinase, which is differentially expressed in proliferating T cells, has demonstrated potential for evaluating response during dendritic cell immunotherapy of glioma in preclinical and clinical studies." (PMID 34321569, 2021).
intrahepatic cholangiocarcinoma (1 paper, 2017). A carcinoma that arises from the intrahepatic bile duct epithelium in any site of the intrahepatic biliary tree. "Positive dCK expression were observed in 8/31 (26%) in extrahepatic cholangiocarcinoma, 8/22 (36%) in GB cancer, and 5/13 (38%) in intrahepatic cholangiocarcinoma." (PMID 29113399, 2017).
lung adenocarcinoma (1 paper, 2022). A carcinoma that arises from the lung and is characterized by the presence of malignant glandular epithelial cells. "HCC827 lung adenocarcinoma cells exhibited the lowest SAMHD1 expression among CCLE-annotated solid tumor cells and were highly susceptible to PNPi/dG in a dCK-dependent manner." (PMID 35653193, 2022).
monocytic leukemia (1 paper, 2024). "In monocytic leukemia cell lines (THP-1 and U937), the results showed an increased ratio of deoxycytidine kinase/cytidine deaminase (dCK/CDA) gene expression, which further enhanced 1-induced DNA damage." (PMID 38535455, 2024).
ovarian sarcoma (1 paper, 2017). A rare, aggressive malignant mesenchymal neoplasm that arises from the ovary. "The specificity of the interaction between masitinib and dCK was next validated in vitro on three cell line lysates (HMC-1.1, HRT18 and Messa 10K (human ovarian sarcoma cell line)) by pull-down and western blotting, using the NH2-modified masitinib probe." (PMID 29127277, 2017).
pancreatic adenocarcinoma (1 paper, 2025). "Gemcitabine hydrochloride, an antimetabolite used for pancreatic adenocarcinoma in humans, requires phosphorylation in the intracellular environment by the enzyme deoxycytidine kinase, encoded by the DCK gene." (PMID 40872698, 2025).
uterine sarcoma (1 paper, 2012). "The 6 clones isolated in the preliminary screening were further characterized for the ability of their transgenes to induce sensitization to Gemcitabine in the Messa10K cell line, uterine sarcoma cells that express an inactive dCK and are, therefore, highly resistant to this drug." (PMID 22927829, 2012).
tumor (70 papers, 2006 to 2026). "In tumor cells, DCK inhibition causes gemcitabine resistance, while CDA suppression results in gemcitabine chemosensitivity." (PMID 34458141, 2021). "A CpG island exists in the promoter region of the DCK gene 22, and several studies focused on the possible association of its methylation status with the sensitivity to nucleoside analogs in tumor samples." (PMID 29473342, 2018). "The presence of WT dCK caused the irradiated tumor to retain significantly more [18F]-FAC compared to un-irradiated tumor." (PMID 25101980, 2014). "The appearance of resistance forms among tumor cells, often due to a loss of dCK activity, and the toxicity of high concentrations of nucleoside analogues for non-tumor cells, constitute the major limits of the treatments with these compounds." (PMID 22927829, 2012). "We isolated a dCK variant inducing death in tumour cells at doses up to 300 times lower than those required for killing non-engineered cells." (PMID 22927829, 2012). "The presence of dCK+ cells was associated with nodal status and by trend with tumor size." (PMID 31307406, 2019). "Our results suggest that pp32 expression levels directly disrupt or facilitate HuR's ability to support cancer cell viability and proliferation by disrupting the stabilization of mRNA transcripts encoding proteins necessary for tumor cell survival, such as dCK, VEGF, or HuR." (PMID 21152064, 2010). "Based on their strong safety profile and unique mechanism of action, dCK inhibitors are a promising companion for established treatments that induce DNA damage or restrict de novo pathway activity in tumor cells." (PMID 40519286, 2025). "dCK inhibition is a promising anti-cancer treatment strategy, as tumor cells exhibit an increased demand for pyrimidine nucleotide synthesis to fuel DNA replication and repair." (PMID 40519286, 2025). "The scatter plots illustrated that DCK and POLR2L in the signature were significantly associated with tumor immune microenvironment through single cell analysis based on GSE140228, GSE98638, GSE146115, GSE146409, GSE166635, GSE179795." (PMID 38517376, 2024). "Once gemcitabine enters the tumor cell, it is phosphorylated by deoxycytidine kinase (DCK) as a first step towards its active and cytotoxic form difluorodeoxycytidine triphosphate (dFdCTP)." (PMID 38744194, 2024). "According to the GEPIA database, DCTD is ubiquitously expressed across various tissues while DCK is upregulated in at least 11 tumor types." (PMID 37378658, 2023). "CP-4126 was reported to traverse cell membranes by passive diffusion, followed by intracellular conversion to GEM by esterases in plasma and within tumor cells to be activated, and it is also dependent on dCK for phosphorylation." (PMID 35656081, 2022). "Once transported into tumour cells, dFdC is phosphorylated into dFdCMP and dFdCDP by deoxycytidine kinase (dCK), pyrimidine nucleoside monophosphate kinase (also known as UMP/CMP), and nucleoside diphosphate kinase successively." (PMID 32677676, 2020). "dCK is the rate-limiting enzyme of the process of the metabolism of gemcitabine, of which the levels of expression in tumour cells are intimately correlated with the activation and inactivation of gemcitabine." (PMID 32677676, 2020). "By the activity of DCK, drugs will be “trapped” inside tumor cells, leading to a higher concentration and longer retention time of these drugs in the tumor, and thus an observable increase in CEST contrast in the delayed phase." (PMID 33374213, 2020). "Third, LDH-A dedicates to the formation of chemoresistance of CSCs, as NHI can stimulate the releasing of deoxycytidine kinase (dCK), which can enhance the anti-tumor efficiency of Gemcitabine." (PMID 28009990, 2017). "It is known that many nucleoside analogs are used in combination with radiotherapy and deoxycytidine kinase (dCK) is required for the anti-tumor activity of these nucleoside analogs." (PMID 27879648, 2016).